YAP1 (Yes1 associated transcriptional regulator)
Diseases named in the same sentence as YAP1 in open-access papers (continued):
Sharing a sentence is not in itself a finding about the gene and the disease.
cancer (continued). "ZEB1 turns into a transcriptional activator by interacting with YAP1 in aggressive cancer types." (PMID 28953220, 2017). "Our experimental findings implicate a crucial role for platelets in inducing anoikis resistance and in metastatic spread of cancer cells intraperitoneally and hematogenously by inducing a YAP1-dependent transcriptional program in detached cancer cells, which promotes cell survival and metastasis." (PMID 28827520, 2017). "The YAP1/TAZ transcription adaptor proteins are important controllers of cancer cell survival." (PMID 29088716, 2017). "Our study adds an important new function for YAP1 that may be relevant to cancer stem cells, drug resistance and cancer therapy." (PMID 27911857, 2017). "YAP1, an identified oncogenic transcriptional co-activator and a downstream mediator of the evolutionarily conserved Hippo pathway, has recently become a molecular target for cancer therapy." (PMID 29228705, 2017). "Based on these reports showing YAP1 role in cancer drug resistance, we hypothesized that YAP1 likely contributes to radiation therapy resistance in TNBC." (PMID 29228705, 2017). "Here, we demonstrated for the first time that YAP1 played a key role in colon tumorigenesis in a dual dimensional fashion where it acts in cancer cells to promote the malignant phenotypes including cancer stem-cell like properties and in polarizing TAMs toward M2 phenotype." (PMID 28241877, 2017). "We also used lentiviral vectors to overexpress or silence YAP1 expression in the K1 PTC cell line so that we could investigate the effects of YAP1 on cancer cell proliferation." (PMID 28036290, 2017). "Furthermore, YAP1 upregulation is known to be related with resistance to anticancer drugs such as docetaxel, cisplatin, and cetuximab in several cancers." (PMID 29340043, 2017). "Dysregulation of this pathway has been shown to lead to aberrant stabilization and activation of YAP1/TAZ protein, resulting in tumorigenesis, progression, metastasis, and recurrence, and further causing drug resistance by acquisition of cancer stem cell-like properties." (PMID 29212185, 2017). "As the LATS1, YAP1, ∆Np63α cascade is a potent driver of cancer stem cell survival, we decided to determine whether SFN can suppress activity in this cascade as a mechanism to suppress ECS cell survival." (PMID 29088716, 2017). "Alternatively, EMT could be driven by YAP1, another transcriptional driver that increases cancer stemness and EMT in multiple systems." (PMID 26986722, 2016). "The two gene fusions are the only consistent genetic alterations of WWTR1 and YAP1 in a cancer." (PMID 27129148, 2016). "A recent study also reported that β-Catenin-driven cancer cells required Yap1 to survive." (PMID 26695440, 2016). "Many previous studies have explored the relationship between YAP1 and various types of cancer." (PMID 26263504, 2015). "Interestingly, Snail, CD44, G3BP2, and YAP1 are targets of Wnt5A, a gene involved in invasion and metastasis of many cancers, that is regulated by NF-κB signaling pathway." (PMID 25738332, 2015). "As expected, we also identified 1,142 SF268- and 2,510 NCI-H2052-specific YAP1 binding sites using stringent thresholds but only 48% and 36%, respectively, were assigned to genes not targeted by shared peaks suggesting a common function for YAP1 in cancer cells." (PMID 26295846, 2015). "As emerging regulators of cancer stemness, growth and malignant progression, the two closely related transcriptional regulators YAP1 and TAZ are drastically down-modulated by SNAI2 gene silencing, whereas TAZ in particular is also up-regulated by SNAI2 over-expression." (PMID 25686823, 2015). "Importantly, depletion of TEADs using siRNAs resulted in reduced YAP1 occupancy at cell type-specific and shared loci confirming the general observations made in the cancer cell lines." (PMID 26295846, 2015).
cancer (continued). "Meanwhile, some different researchers argued that YAP1 could also be regarded as a tumor suppressor gene in some malignancies, which generally benefits cancer prognosis." (PMID 26263504, 2015). "The role of YAP1 in cancer development still remains controversial." (PMID 26263504, 2015). "This work establishes YAP1-mediated transcriptional regulation at distal enhancers and provides an expanded set of target genes resulting in a fundamental source to study YAP1 function in a normal and cancer setting." (PMID 26295846, 2015). "Both overall and nuclear YAP1 overexpression are intimately associated with adverse OS and DFS in numerous cancers, suggesting that YAP1 may act as a potential therapeutic targets of these malignancies in the future." (PMID 26263504, 2015). "In addition, in transgenic mouse models the liver-specific YAP1 overexpession induced a dramatic increase of liver organ size, eventually leading to cancer development." (PMID 24810989, 2014). "Because YAP1 is also activated in many other types of cancers, the oncogenic activation of YAP1 induced by smoking may be a common mechanism for the carcinogenic effects of cigarette smoking." (PMID 24621512, 2014). "It has been shown that yap1 expression is activated during cancer development." (PMID 24598795, 2014). "Notably, we detected a significant increase of the protein levels of p21 and p27, which are implicated in the negative regulation of cell-cycle, in YAP1 silenced cells compared to the off target cells in all YAP1-amplified cancer cell lines." (PMID 24810989, 2014). "Notably, homozygous deletion encompassing YAP1 gene was a very rare event, in fact it was found only in 3/664 (0.5%) cancer cell lines and in 3/1629 (0.2%) cancer tissue samples." (PMID 24810989, 2014). "In addition, we directly detected that YAP1 amplification is actually present in a variable but significant fraction of carcinoma subtypes." (PMID 24810989, 2014). "The level of phospho-YAP1 (p-YAP1) protein, which is only detected in the whole cell lysate and the cytosolic fraction in the cell lines, also confirms the differences in YAP1 cellular localization between the cancer cell lines and HPDE6." (PMID 22396793, 2012). "Overall, these findings suggest that YAP1's expression and role in cancer might be cell type and/or cellular context dependent." (PMID 22396793, 2012). "Thus, developing alternative strategies to destabilize YAP1 might improve the clinical outcome of lethal cancers harboring aberrantly upregulated YAP1." (PMID 39827153, 2025). "Thus, targeting upstream regulators of YAP1 turnover might be an appealing strategy for the treatment of YAP1-driven cancers." (PMID 39827153, 2025). "Thus, identifying more actionable therapeutic drugs that destabilize YAP1 may significantly improve clinical outcomes in cancers with upregulated YAP1, including CRC." (PMID 39968498, 2025). "Additionally, sex-determining region Y-box transcription factor 2 (SOX2) and NANOG, which are markers of cancer stem cells, have been implicated in ESCC progression, but their regulation through PP1γ and YAP1 remains unclear." (PMID 40626009, 2025). "Our results demonstrated that LSD1 can upregulate YAP1 expression and promote stem-like properties in TNBC largely by repressing the transcription of METTL14, suggesting that the loss of METTL14 is another mechanism critical for the function of LSD1 in determining the aggressiveness of cancer cells." (PMID 39563370, 2024). "In differentiated epithelial-like cancer cells, loss of PARD3 has been extensively reported to regulate HIPPO signalling for the expansion of the cell population by directly interacting with and dephosphorylating YAP1 via its PDZ domain, which is essential for YAP1 activation." (PMID 38317186, 2024). "Furthermore, YAP1 has been shown to drive cancer metastasis." (PMID 38444414, 2024).
cancer (continued). "For example, upregulation of heat shock factor 1 (HSF1), Yes-associated protein 1 (YAP1), Stromelysin 1 and stromal-derived exosomes have emerged as mediators of cancer progression through enhancing cancer cell motility, invasion, metabolic reprogramming and inducing cancer stem cell features." (PMID 35642343, 2023). "5-FU-miR-15a was also shown to significantly inhibit the expression of Yap1, Bcl2, Il6, and Mmp9, both alone and during treatment with TGFβ1 in murine and human Pancreatic Stellate Cells, suggesting the reduced proliferation and migration of pancreatic stellate and cancer cells." (PMID 38139352, 2023). "Taken together, GNB4 may have a cancer-promoting function through the Hippo–YAP1 pathway." (PMID 37016382, 2023). "Importantly, Yes-associated protein (YAP1), a critical component of the Hippo pathway and co-activator of genes related to EMT and cell growth, was also highly upregulated in cancer cells upon direct contact with fibroblasts." (PMID 36936987, 2023). "In addition, the complexation of YAP1 and β-catenin is reported in cancer cells." (PMID 37793774, 2023). "Hence, SKP2, instead of CDC20, positively correlates with YAP1 expression in pan-cancer." (PMID 35685435, 2022). "Finally, YAP1 activation is emerging as a mechanism of resistance to cancer therapies." (PMID 35689194, 2022). "Interestingly, the transcriptional regulator YAP1 may be significantly involved in the upregulation of MALAT1 gene expression in cancer cells." (PMID 35922756, 2022). "AZD2858 and varlitinib might be effective in cancer patients with high YAP1 expression." (PMID 36479120, 2022). "Of the 218 FDA-approved drugs, chemotherapeutic agents that inhibit DNA synthesis (teniposide, dacarbazine, doxorubicin, triethylenemelamine, nitrogen mustard, etoposide, and thiotepa) topped the list, which might be effective in treating cancer patients with high YAP1 expression." (PMID 36479120, 2022). "The Yes Associated Protein 1 (YAP1) gene encodes a downstream nuclear effector of the Hippo signaling pathway, which is known to play a role in the development and progression of multiple cancers, by acting as a transcriptional regulator of this signaling pathway." (PMID 35282432, 2022). "Thus, verteporfin may be a potential cancer-stem-cell-based approach in GC therapy targeting YAP1/TAZ-TEAD activity." (PMID 36615513, 2022). "The function of YAP1 in CAFs of other cancer types remains largely unknown." (PMID 36479120, 2022). "Based on the current result and previous reports, we can speculate that during the early stage of cancer, when cancer cells exhibit low malignancy, YAP1‐1 binds weakly to negative regulators and shows higher protein stability and nuclear localization than YAP1‐2." (PMID 35014181, 2022). "Therefore, we would like to discuss in more detail the role of YAP1 in these cancer types." (PMID 36479120, 2022). "Moreover, YAP1 has exhibited oncoroles in a variety of cancer." (PMID 35601153, 2022). "The cellular crosstalk between Hippo/YAP1 and Wnt/β-Catenin pathways is not fully understood, but increasing evidence have shown that both are able to coordinately regulate gene expression and signaling with relevance to cancer cell migration and metastatic formation." (PMID 34395416, 2021). "Anxa2 has been proven facilitating cancer progression via multiple aspects by interacting with other biomolecules, among which the Anxa2 rearrangement gene expression in cancer cells through oncogenic transcription factor like NF-κB, YAP1 in Hippo pathway and STAT3/6." (PMID 34502195, 2021). "On the one hand, the degradation of YAP1 may be a choice for cancer treatment." (PMID 34150758, 2021).
cancer (continued). "Moreover, the underlying mechanisms were uncovered, and we evidenced that ANXA6-exo up-regulated YAP1 to promote Hippo pathway dysregulation, and the promoting effects of ANXA6-exo on PTX resistance and cancer aggressiveness in BC cells were abrogated by silencing YAP1." (PMID 34676207, 2021). "This raised the possibility that the amplification of YAP1 may contribute to cancer development." (PMID 34150758, 2021). "It is possible that, due to such a negative feedback mechanism, simple overexpression of wild-type YAP1 may not be sufficient to trigger long-lasting proliferative events, which may partially explain the relative lower frequencies of YAP1 amplification in human cancers." (PMID 34150758, 2021). "Clinically, YAP1 could be a target for the development of cancer drugs." (PMID 34132347, 2021). "It has been identified that YAP1 activity positively correlates with chemoresistance, tumor heterogeneity, mesothelial-to-mesenchymal transition, fibrosis, metastasis and frequency of self-renewing cancer stem cells in different types of tumors, including liver cancer." (PMID 33260691, 2020). "Notably, all three YAP1/WWTR1 compensable cell lines (BICR10, HSC-2 and HSC-4) harbor PIK3CA mutation, and that alterations in the PI3K signaling pathway have been linked to multiple metabolic dysregulations in cancer." (PMID 32990596, 2020). "Moreover, we found that decreased expression of YAP1, by siRNA pool transfection, significantly reduced the migration capacity of GB-d1 and G-415 cancer cells to 54.3% (p = 0.0404) and 30.0% (p = 0.0097) compared to control siRNA-transfected cells, respectively." (PMID 32218280, 2020). "YAP1 is overexpressed in EAC cell lines relative to BE cell lines, thus suggesting that loss of miR-375 in EAC may promote proliferation and invasion of cancer cells." (PMID 31934893, 2020). "Interestingly, the vast majority of genes in the core SOH signature were upregulated in the SOH subgroups across the four cancer types, suggesting that many of these genes might be direct targets of YAP1/TAZ, which are best known as transcription activators." (PMID 32717825, 2020). "Our study inferred that Clostridium induced YAP1 activation, which in turn suggested that the suppression of Clostridium by antibiotics and/or oral hygiene might contribute to the suppression of carcinogenesis and cancer progression." (PMID 32064037, 2020). "YAP1 may be used as a potential target for new targeted cancer therapy." (PMID 32066485, 2020). "Furthermore, results from large number of patients with CRC suggested that high expression of YAP1, TEA domain family member 2(TEAD2) and YAP1 target genes cysteine-rich angiogenic inducer 61 (CYR61) and ankyrin repeat domain 1 (ANKRD1) were associated with a high risk of cancer relapse." (PMID 32503256, 2020). "Therefore, it is critical to investigate the relationship between YAP1 and cancer." (PMID 31613226, 2019). "Interestingly, YAP1 in these cells also contributes to cancer progression." (PMID 31137841, 2019). "Increasing evidence suggests that YAP1 has diverse roles in tumorigenesis and drug resistance, and it has been reported to promote malignant features (e.g., cell proliferation, invasion, migration, and anti-apoptosis) and drug resistance in various cancers, including breast, bladder and lung cancer." (PMID 31137841, 2019). "Therefore, we evaluated by a meta-analysis the prognostic value of YAP1 in cancer patients." (PMID 31613226, 2019). "Yap1 is known to play a role in the development and progression of multiple cancers as a transcriptional regulator and may function as a potential target for cancer treatment." (PMID 31455378, 2019). "Since cLIF cells exhibited a higher activity of SRC and consequently an enhanced EMT and invadopodia formation, we therefore investigated whether treatment of cancer cells with AZD0530 alters LIF-regulated expressions of p-YAP1 and focal adhesion molecules, which might affect SRC activity." (PMID 30504771, 2018).
cancer (continued). "Here, we described the generation, validation and characterization of a Yap1/Taz zebrafish reporter, which represents a powerful tool to follow this signaling activity in a living vertebrate, offering also interesting applications in drug screening, cancer and regenerative biology." (PMID 29976931, 2018). "The oncogenic role of YAP1 may depend on the biology of primary cancer type." (PMID 29850494, 2018). "However, the molecular mechanisms driving YAP1 activation in cancer are still poorly defined." (PMID 29985391, 2018). "Indeed, carcinoma cells with activated YAP1/TAZ are resistant to chemotherapeutic drugs." (PMID 28782275, 2018). "Notably, multiple miRNAs have been reported to regulate YAP1 expression in many cancers." (PMID 28915618, 2017). "Moreover, compelling evidence supports a role of YAP1/TAZ in cancer stem cells." (PMID 27911857, 2017). "Indeed, YAP1 is overexpressed in several human cancers and tumorigenic models." (PMID 29113304, 2017). "These known NF-κB target genes, such as IL6, IL8, BIRC2 (clAP-1), ICAM1, YAP1, CDKN1A (p21), CSF2, CCDN1, IL1A, IL1B, and so on, include many that have been independently confirmed to be differentially expressed and pathologically implicated in HNSCC and other cancers." (PMID 18334025, 2008). "Here, we concluded recent data providing distinct thoughts about YAP1/TAZ among cellular metabolism, cancer progression, and drug resistance." (PMID 40977060, 2025). "Understanding these intricate mechanisms is paramount for developing therapeutic strategies targeting YAP1/TAZ in human diseases, particularly cancer." (PMID 40977060, 2025). "Inflammatory factors (IL-6, STAT3, YAP1, NF-κB, COX-2/PGE2, and NO) induce stemness, which promotes cancer progression." (PMID 40244228, 2025). "The AMPK pathway is a known regulator of cancer growth and progression, inhibiting several other pro-cancer pathways including mToR, HIF-1α, β-catenin, and Yap-1." (PMID 39941833, 2025). "We recently demonstrated that cancers can be functionally stratified into just two types based on distinct expression and function of the transcriptional co-activators, YAP (YAP1) and TAZ (WWTR1)." (PMID 40440076, 2025). "Increased activity of YAP1, in conjunction with its binding partner TEAD, was previously shown to promote proliferation and metastasis in multiple cancers, including HNSCC." (PMID 39622638, 2025). "When these factors are abnormal, YAP1/TAZ signaling pathway is exceptionally activated in multiple diseases, such as cancer, fibrosis, inflammation, and atheromatous disease." (PMID 40977060, 2025). "First, we analyzed the gene expression profiles of 33 cancer types from the TCGA database and found that the expressions of ROCK1 and YAP1 were positively correlated." (PMID 40368918, 2025). "Our study elucidates EGCG’s inhibitory action on the overexpressed YAP-1/TEAD/CTGF axis in OSI-resistant clones, synergistically displaying anti-cancer activity by re-sensitising cells to OSI." (PMID 40922739, 2025). "This approach is particularly relevant in cancers with high ferroptosis sensitivity, such as those exhibiting EMT features and activated YAP1/TAZ signaling." (PMID 40075648, 2025). "Although point mutations in core Hippo components are relatively rare, amplification of YAP1 and WWTR1 (TAZ) is more frequent in specific cancers, particularly squamous cell carcinoma and ovarian cancer." (PMID 41028521, 2025). "In summary, we demonstrated that STK3, against the common knowledge, is transcriptionally regulated by YAP1, and the high expression of STK3 can promote GC progression by manipulating cancer cell malignance." (PMID 40604818, 2025). "YAP1 induces expressions of CTGF, CYR61, and other target genes, contributing to cancer stemness, chemoresistance, metastasis, and poor prognosis." (PMID 39968498, 2025). "By further subgrouping the cancer cells, the STK3+ and YAP1+ cells were classified into the same Seurat clusters (cluster 4 and 5)." (PMID 40604818, 2025).